LDHB (lactate dehydrogenase B)
Diseases named in the same sentence as LDHB in open-access papers (continued):
Sharing a sentence is not in itself a finding about the gene and the disease.
Sepsis (2 papers, 2025). Sepsis is defined as life-threatening organ dysfunction caused by a dysregulated host response to infection. "•Identified 4 diagnostic genes (APRT, ARG1, UMPS and LDHB) for sepsis prognosis." (PMID 40774030, 2025). "Four diagnostic genes (APRT, ARG1, UMPS and LDHB) with excellent diagnostic value were identified, which might be mainly concentrated in energy metabolism-related functions and the immune-related pathway in the Sepsis process." (PMID 40774030, 2025). "Consistent clustering of Sepsis samples in GSE65682 dataset was conducted based on four diagnostic genes (APRT, ARG1, UMPS, LDHB) associated with patient survival." (PMID 40774030, 2025). "Interestingly, the authorsfound high expression of LDHA and low expression of LDHB in patients with Sepsis." (PMID 40774030, 2025). "Promoting LDHB expression and activity may be a potential therapeutic method for reducing hyperlactemia and treating Sepsis." (PMID 40774030, 2025). "APRT, ARG1, UMPS, and LDHB might be new ideas for studies related to the diagnosis and treatment of Sepsis." (PMID 40774030, 2025). "LDHA is responsible for the conversion of pyruvate to lactate and NAD+, while LDHB is responsible for the conversion of lactate to pyruvate and promotes oxidative metabolism, which suggests that hyperlactemia is an independent predictor of Sepsis death." (PMID 40774030, 2025). "The authorsfound high expression of LDHA and low expression of LDHB in Sepsis patients." (PMID 40774030, 2025). "Ultimately, by taking the intersection of the results from the three machine learning methods, we identified six feature genes in sepsis: CD81, CLU, GLRX, CKAP4, DPEP2, and BCL11B; and seven feature genes in atrial fibrillation: LDHB, CD81, PFKFB2, CKAP4, CXCR4, DPEP2, and RORA." (PMID 41359645, 2025).
atrial fibrillation (1 paper, 2025). A disorder characterized by an electrocardiographic finding of a supraventricular arrhythmia characterized by the replacement of consistent P waves by rapid oscillations or fibrillatory waves that vary in size, shape and timing and are accompanied by an irregular ventricular response. "In the selection of feature genes for atrial fibrillation, LDHB, DPEP2, BCL11B, CKAP4, RORA, PFKFB2, and CXCR4 were identified as potentially important predictors, with the model error being lowest when the number of genes reached eleven." (PMID 41359645, 2025). "In the atrial fibrillation dataset, LDHB, PFKFB2, CKAP4, CXCR4, DPEP2, and RORA genes showed an upregulation trend, while only the CD81 gene was downregulated in the disease group." (PMID 41359645, 2025). "In the immune cell correlation analysis of atrial fibrillation feature genes, we observed that CXCR4 was negatively correlated with regulatory T cells and Macrophages M2, while LDHB was positively correlated with gamma delta T cells, and DPEP2 was positively correlated with CD8 T cells." (PMID 41359645, 2025).
benign breast tumors (1 paper, 2020). "Interestingly, in adipose tissue, LDHB was preferentially expressed in cancer-associated adipocytes in comparison to adipocytes found in benign breast tumors." (PMID 33353120, 2020).
bone fracture (1 paper, 2020). "We found that both LDHB and UGCG were increased in bone fracture patients, but only UGCG was significantly lower in the nonunion group, with no significant changes during DR treatment." (PMID 32503597, 2020).
carcinoid tumor of the lung (1 paper, 2013). "Compared to the carcinoid tumor of the lung, significantly increased expression of LDHB and hnRNPF was found in 16/16 and 11/16 fresh MCC tumors, respectively." (PMID 25284964, 2013).
cognitive deficits (1 paper, 2022). "Moreover, LDHB deficiency-induced gliosis increased the production of inflammatory mediators (TNF-α, Nf-ĸB, and NOS2), and revealed cognitive deficits." (PMID 35204143, 2022).
colitis (1 paper, 2025). Inflammation of the colon. "Furthermore, histological examination found increased inflammation in these same colons confirming that transfer of LDHB expressing pDCs into infected mice associated with increased colitis." (PMID 39920132, 2025). "This is associated with enhanced IFNAR dependent infection-induced-colitis when LDHB expressing pDCs are transferred into infected mice, suggesting the conservation of pDC inhibition after infection may be a mechanism to avoid excessive pathology." (PMID 39920132, 2025).
Dravet syndrome (1 paper, 2022). "Therefore, we took advantage of the use of stiripentol, an antiepileptic drug approved by the FDA for the treatment of Dravet Syndrome, because it also potently inhibits both LDHA and LDHB activity." (PMID 36278433, 2022).
esophageal cancer (1 paper, 2022). A primary or metastatic malignant neoplasm involving the esophagus. "To assess whether TNF-α is involved in the regulation of LDH in esophageal cancer cells, we analyzed the expression levels of genes encoding LDH subunits (LDHA and LDHB) in TNF-α-treated KYSE150 and EC7 cells versus untreated cells using qPCR." (PMID 36555705, 2022).
fluorosis (1 paper, 2023). "The top 10 drugs have been reported in previous studies, namely Celastrol, LDN-193189, XPNPEP1, GNB5, Importazole, LDHB, NUAK1, IFNG, IFNB1, and YWHAH, suggesting that these drugs may be effective candidate drugs for the treatment of fluorosis." (PMID 36835629, 2023).
Follicular Cyst (1 paper, 2023). Cyst due to the occlusion of the duct of a follicle or small gland. "In our study, the LDHB gene was significantly up-regulated in the TIMG cells of follicular cysts, and there was a mutation in the 5′-untranslated region of LDHB, indicating that increased LDH correlated with the occurrence of follicular cysts." (PMID 38274662, 2023). "We compared transcriptomic data from follicular cysts to the reference genome and identified non-synonymous mutations in three genes: IBSP, LDHB and PRLR." (PMID 38274662, 2023). "These genes are involved in several pathways involved in follicular cyst formation: ECM-receptor interaction (IBSP), PI3K-Akt signaling pathway (IBSP and PRLR) and metabolic pathways (LDHB)." (PMID 38274662, 2023).
follicular thyroid carcinoma (1 paper, 2013). "Our results show that ERRα regulates LDH activity by direct interaction with the LDHB promoter in cellular models of follicular thyroid carcinoma, and that PRC may interact with ERRα to decrease LDH activity and modulate the LDHA/LDHB expression ratio." (PMID 23516535, 2013).
ischemic stroke (1 paper, 2024). A stroke disorder caused by obstruction of blood flow to the brain, due to thrombotic (local blood clot formation) or embolic (due to a blood clot or other material traveling from another site) event. "After external validation with eQTL dataset, lactate dehydrogenase B (LDHB) is identified to be positively associated with ischemic stroke." (PMID 38702940, 2024).
lactic acidosis (1 paper, 2019). Metabolic acidosis characterized by the accumulation of lactate in the body. "LDHB was also greater at warmer temperatures which is consistent with the observation that lactic acidosis in white muscle and blood generally increases with warmer temperatures in rainbow trout and steelhead." (PMID 31191906, 2019).
leiomyoma (1 paper, 2016). A well-circumscribed benign smooth muscle neoplasm characterized by the presence of spindle cells with cigar-shaped nuclei, interlacing fascicles, and a whorled pattern. "In addition, PTRF co-expresses with KRT1, CCT5 co-expresses with MHI1; GOT1 co-expresses with MHI1; and MHI1 co-expresses with LDHB; indicating not only an interaction between LDHB, GOT1 and MDH1, but also a possible association between them and the leiomyoma." (PMID 27070597, 2016).
lung fibrosis (1 paper, 2023). "Collectively, our in vitro and IHC results consistently suggest that the alteration of LDHA/LDHB and GPR‐81 is associated with the fibrotic process and may contribute to the development and progression of lung fibrosis." (PMID 37653539, 2023). "Because IMR‐90 fibroblasts are derived from fetal lungs and aging contributes to the development of lung fibrosis, we next examined LDHA and LDHB expression in age‐matched control and IPF fibroblasts under normoxic and hypoxic conditions." (PMID 37653539, 2023).
lung large cell carcinoma (1 paper, 2025). A poorly differentiated non-small cell lung carcinoma composed of large polygonal cells without evidence of glandular or squamous differentiation. "Indeed, the flow cytometry-based measurement of the fluorescence level of intracellular oxidized C11-BODIPY revealed that LDHB silencing significantly increased total cellular lipid peroxidation in A549 cells and also in H460 cells, a lung large cell carcinoma cell line." (PMID 40090955, 2025).
lymph node metastasis (1 paper, 2015). "However, LDHB expression was markedly associated with pathological grade (P = 0.037), vascular invasion (P = 0.037), lymph node metastasis (P = 0.016), and TNM stage (P = 0.007)." (PMID 26426634, 2015). "By Cox regression, low LDHB expression (P = 0.045) and lymph node metastasis (P = 0.04) indicated a poor DFS." (PMID 26426634, 2015). "Furthermore, LDHB expression was negatively correlated with pathological grade, vascular invasion, lymph node metastasis, and TNM stage." (PMID 26426634, 2015). "Finally, we screened the prognostic factors LDHB expression and lymph node metastasis for DFS and LDHB expression for OS." (PMID 26426634, 2015).
lymphoma (1 paper, 2024). A malignant (clonal) proliferation of B- lymphocytes or T- lymphocytes which involves the lymph nodes, bone marrow and/or extranodal sites. "Among all genes, lactate dehydrogenase genes (LDHA and LDHB) were observed to be the most highly expressed (among the entire transcriptome), followed by transaminase genes (GOT1, GOT2, GPT, and GPT2) with log2 median expression > 10, both in lymphoma patients and cell lines." (PMID 39518046, 2024).
metastatic cancers (1 paper, 2021). A carcinoma which has spread from the original site of growth to another anatomic site. "Unlike that seen for LDHA, metastatic cancers usually show reduced LDHB expression due to promoter hypermethylation or altered glycolytic signaling; low LDHB levels have been associated with poor prognosis in different cancers." (PMID 33804985, 2021).
non-alcoholic steatohepatitis (1 paper, 2023). "In human and mouse non-alcoholic simple fatty livers as well as non-alcoholic steatohepatitis livers, hyperacetylation of LDHB has been linked to lactate accumulation." (PMID 37239836, 2023).
ocular melanoma (1 paper, 2021). A melanoma that arises from the structures of the eye or ocular adnexa. "Notably, we found either LDHA-deficient (lane 2) or LDHB-deficient (lane 3) ocular melanoma cells did not present with remarkable reduction of global histone lactylation." (PMID 33726814, 2021).
oncocytic tumors (1 paper, 2013). "In thyroid tissues, the LDHA and LDHB expression levels were similar in follicular, oncocytic tumors and normal tissues." (PMID 23516535, 2013). "In thyroid tissues the ratio was higher for normal thyroid tissues than for follicular tumors or oncocytic tumors.Thus, the LDHA/LDHB ratio was similar in follicular and oncocytic tumors and their corresponding cell line models, FTC-133 and XTC.UC1." (PMID 23516535, 2013).
prostate tumors (1 paper, 2019). "We have demonstrated the prognostic features of FGFR1, FRS2, S6K1, LDHB, MYPT1, and P-LDHA in prostate tumors using tissue microarrays (TMAs) which consist of 241 patient samples from Massachusetts General Hospital (MGH)." (PMID 31316912, 2019).
Renal cyst (1 paper, 2024). A fluid filled sac in the kidney. "The upregulation of LDHA (1.4×) and downregulation of LDHB (−1.8×) in renal cysts suggest increased pyruvate to lactate flux." (PMID 39000280, 2024).
renal oncocytomas (1 paper, 2017). "Lactate dehydrogenase B levels were even decreased in renal oncocytomas." (PMID 29285300, 2017).
Zinc deficiency (1 paper, 2025). A deficiency of the essential metal Zinc; an essential cofactor for many enzymes. "Our findings demonstrated a substantial upregulation of both LDHA and LDHB expression under zinc deficiency conditions, further supporting the accumulation of lactic acid and intracellular pH reduction in zinc-deficient rat cells." (PMID 39028478, 2025). "Furthermore, lactic acid level reduction and normalization of LDHA and LDHB expression in the ZS group suggested that zinc supplementation effectively regulates energy metabolism imbalance induced by zinc deficiency." (PMID 39028478, 2025).
tumor (190 papers, 2011 to 2026). "LDHB, a key enzyme in lactate metabolism, has been implicated in enhancing glycolytic activity and driving tumor cell proliferation across various cancer types." (PMID 40977852, 2025). "The lactate dehydrogenase isoenzymes (LDH) are tetramers composed of LDHA and LDHB, and their aberrant expression is often associated with cellular metabolism and tumor progression." (PMID 38511143, 2024). "IHC analysis revealed that LDHA and LDHB expression profiles were significantly associated with tumor grade, stage, size, and overall survival (OS)." (PMID 37547725, 2023). "Compared with the WT BMDCs, the LDHA/LDHB-deficient BMDCs were less potent in suppressing tumor growth and inducing tumor-infiltrating IFN-γ–producing T cells." (PMID 36821379, 2023). "Univariate statistical analysis found that LDHB‐Ac‐K329 levels were negatively associated with tumour size (P = 0.004) and histological grade (P = 0.031)." (PMID 30443978, 2019). "There is also a loss of LDHB-abolished cell proliferation in vitro, and an arrested tumor growth in vivo." (PMID 31035592, 2019). "Tumor cell lines with high levels of LDHB are more sensitive to a loss of LDHB (p = 0.00005) compared to LDHB low-expressing lines." (PMID 31035592, 2019). "LDHB knock down inhibited cell growth, proliferation, and invasion and the loss of LDHB was shown to arrest tumor growth in vitro an in vivo." (PMID 29326883, 2017). "The underlying mechanism seems to involve LDHB promoter hypermethylation and consequent gene silencing at the transcriptional level, but exactly how loss of LDHB contributes to tumor progression is not clearly understood." (PMID 29326883, 2017). "Indeed, we recently demonstrated that LDHB suppresses mitochondria-associated ferroptosis, a process linked to the accumulation of lipid peroxidation in various tumor types." (PMID 40790017, 2025). "In parallel, the downregulation of LDHB in macrophages increases lactate accumulation and promotes histone lactylation, thereby facilitating M2-like polarization and tumor-associated macrophage formation within the tumor microenvironment." (PMID 40710349, 2025). "Thus, the observed reduction of tumor growth after LDHB silencing reported by us before is associated with the accumulation of persistent DNA damage." (PMID 40158058, 2025). "Since the host immune system plays a critical role in controlling tumor progression, we reasoned that LDHB loss in HCC cells might attenuate the anti-tumor immune response in vivo." (PMID 38739169, 2024). "LDHA and LDHB are elevated in many tumor types and are associated with tumor growth and invasion." (PMID 38291366, 2024). "Previous reports have associated changes in LDHB expression with tumor progression." (PMID 31086659, 2019). "In addition to its role in tumor metabolism, LDHB has also been implicated in immune cell function." (PMID 37508430, 2023). "However, additional studies will be necessary to elucidate on the molecular level how the modulation of LDHB expression affects the complex interplay between lactate metabolism and stemness pathways that are associated with an increased tumor initiation capacity." (PMID 35877003, 2022). "In HCC, suppressed LDHB expression sustains high lactate levels and aerobic glycolysis, contributing to rapid tumor growth." (PMID 40818043, 2026). "While LDHA's role in tumor metabolism is well‐documented, LDHB functions appear more context‐complex." (PMID 40818043, 2026). "Dysregulated LDH expression, particularly upregulation of LDHA and downregulation of LDHB, promotes tumor progression." (PMID 40818043, 2026). "Reduced expression of LDHB (lactate dehydrogenase B) in BC cells promotes lactate clearance, leading to increased NK cells activity and inhibition of tumor metastasis." (PMID 41415282, 2025).